C8orf58 (chromosome 8 open reading frame 58)
Synonyms: FLJ34715
Tractability: No criterion of Open Targets' tractability assessment is met for any kind of drug.
Gene: Protein-coding gene on chromosome 8 (22,599,594 to 22,604,150, forward strand). Ensembl gene ENSG00000241852.
Subcellular location (Human Protein Atlas): Nuclear bodies; Nucleoplasm
Genetic constraint (gnomAD): Loss-of-function variants: 26 observed, 32.19 expected, observed/expected ratio (o/e) 0.81, 90% interval 0.59 to 1.12. The upper end of that interval is the gene's LOEUF score, 1.12, which puts it in group 4 of 6, group 1 being the genes least tolerant of losing a copy. Missense variants: 513 observed, 445.91 expected, observed/expected ratio (o/e) 1.15, 90% interval 1.07 to 1.24. Synonymous variants: 219 observed, 185.72 expected, observed/expected ratio (o/e) 1.18, 90% interval 1.05 to 1.32.
Homologues: Orthologues: chimpanzee C8orf58 (99% identical), dog C8orf58 (68% identical), pig C8orf58 (68% identical), rabbit C8orf58 (64% identical), mouse 9930012K11Rik (62% identical), guinea pig C8orf58 (60% identical), rat C15h8orf58 (59% identical).
Diseases named in the same sentence as C8orf58 in open-access papers:
C8orf58 is named in the same sentence as 6 diseases in open-access papers, as found by Europe PMC text mining. Sharing a sentence is not in itself a finding about the gene and the disease. The quoted sentences say what the papers report.
papillary thyroid carcinoma (1 paper, 2020). "We found that cg00768487 (UBXN11) and cg03110787 (MLLT1) have been associated with papillary thyroid carcinoma, cg10806146 (SLC20A2) and cg15936066 (SLC20A2) with prostate cancer, cg15936066 (SLC20A2) with systemic lupus erythematosus, and cg07538190 (C8orf58) with psoriasis." (PMID 32493484, 2020).
tumor (1 paper, 2020). "C8orf58 is downregulated in HCC and coexpressed with MEG3 protein, which acts as a suppressor in tumor cells." (PMID 32316112, 2020).
C8orf58 also shares sentences with these, for which no sentence is quoted: cancer (1 paper); prostate carcinoma (1); psoriasis (1); systemic lupus erythematosus (1).